CD44 (CD44 molecule (IN blood group))
Diseases named in the same sentence as CD44 in open-access papers (continued):
Sharing a sentence is not in itself a finding about the gene and the disease.
cancer (continued). "CD44 has also been reported to promote cancer stemness, aggressiveness, and drug resistance in different cancer types." (PMID 34439211, 2021). "Some cancer cells begin to express stem cell markers, such as CD44 and CD34, and their self-renewal, proliferation, and drug resistance are significantly increased." (PMID 34553071, 2021). "We demonstrated that ITPR3 knockdown suppressed cancer stemness by decreasing the CD44 protein level." (PMID 33573671, 2021). "We observed significantly different stroma type among subgroups determined by the expression of cancer stem cell markers particularly by CD44 status (p = 0.0033)." (PMID 33836674, 2021). "Analysis of cancer stem cells marker genes, CD44 and PROM1, by real time PCR showed their significant upregulation in both nandrolone or boldenone treated poPSCs, after 7 or 14 days of culture." (PMID 34769230, 2021). "CD44 protein plays important roles in cancer progression and metastasis possibly via Akt activation and its downstream targets." (PMID 33780455, 2021). "Immunofluorescence of ephrinA5 coupled with the cell surface marker CD44 allowed us to investigate the expression of this ligand in the samples enriched for cancer cells." (PMID 33893375, 2021). "RO5429083, a monoclonal antibody targeting CD44, has been evaluated in clinical trials in malignant solid tumors and acute myelogenous leukemia by Roche." (PMID 34638298, 2021). "In this study, we also found a significant association between Reg4, CD44, and CD44ICD; demonstrating for the first time that this pathway is biologically relevant outside of cancer cell lines alone." (PMID 33659040, 2021). "Antibodies to inhibit the CD44 mediated cancer progression also show remarkable results in inhibition of HA-CD44 downstream pathways." (PMID 34513617, 2021). "The interaction between CD44 and integrins which mediate cancer cell mobility has been documented in multiple studies." (PMID 34944101, 2021). "CD44 is a cell surface glycoprotein that is highly expressed in some cancer stem cells and is closely related to cell motility and cancer metastasis." (PMID 33854593, 2021). "Bromelain can be effective in cancer treatment; it cleaves a cluster of differentiation 44 (CD44) molecules preferentially, thereby inhibiting the first steps of the metastatic process." (PMID 33917319, 2021). "CD44 has also been established as a potential CSC marker that contributes to cancer proliferation, metastasis, and drug resistance." (PMID 34207383, 2021). "This suggests the potential of NSC765600 and NSC765691 to inhibit CCND1/CDK4/PLK1/CD44 expressions in cancer." (PMID 34063946, 2021). "In the hypoxic and hypo-nutritional tumour microenvironment, CAFs expressed higher levels of CD44, which promoted cancer a stem-phenotype including CSCs’ resistance to therapies." (PMID 34572431, 2021). "This suggests the potential of NSC765600 and NSC765691 compounds to inhibit CCND1/CDK4/PLK1/CD44 expressions in cancer." (PMID 34063946, 2021). "The thrust areas that determine the role of CD44 in cancer metastasis and growth are divided into two main categories, one is HA-dependent, and another is HA-independent." (PMID 35431911, 2021). "CD44 is a cell surface transmembrane glycoprotein enriched in breast tumor-initiating cells (or cancer stem cells)." (PMID 34067416, 2021). "We observed NNC and NIC isoforms involving cancer-associated genes such as ERBB2 and CD44 and confirmed previously known FSM isoforms associated with these two genes." (PMID 33482911, 2021). "This review summarises current insights on CD44 structure and isoforms as well as the CD44-mediated oncogenic signalling pathway in several cancers." (PMID 34944493, 2021).
cancer (continued). "Further investigations revealed that osteopontin enhanced HCV replication in a peculiar population of hepatic cells, i.e., CD44+ cancer stem cells." (PMID 34065048, 2021). "By performing qRT-PCR, we observed that cancer cells exposed to SPP1 exhibited a significantly increased gene expression in EMT-related molecule CD44 and glycolytic genes including SLC2A1 and ENO2 at 48 h." (PMID 34676217, 2021). "CD44 and OPN have also been linked to multiple other commonly dysregulated pathways in cancer including but not limited to WNT/beta-catenin and AKT which have also been shown to influence invasion." (PMID 33843470, 2021). "In this study, we established a novel suite of organ-derived metastatic cell lines and subsequently performed a comprehensive transcriptome analysis of cancer progression in relation to CD44 levels." (PMID 34579762, 2021). "CD44, a cell surface adhesion receptor, expresses a high level in various cancers and is involved in multiple signaling pathways in regulating cancer progression." (PMID 34681583, 2021). "The other previous study of BCSC transcriptomes also used the markers CD44 high/CD24 low in two HER2-positive/ER-negative cancers." (PMID 34253873, 2021). "Other than directly targeting CD44, several natural compounds and chemotherapeutic agents can indirectly inhibit the overexpressed CD44 isoforms in cancer cells and CSCs." (PMID 34944493, 2021). "HA-independent cancer signaling of CD44 cells depends on the interactions of the intracellular domain of CD44 cells and cytoskeletal proteins or kinases." (PMID 35431911, 2021). "The interaction of platelets with cancer cells is also mediated by P-selectin, which binds to appropriate ligands, e.g. CD24 and CD44 on cancers." (PMID 33146401, 2021). "As well, CD44 monoclonal antibodies are being assessed in pre–clinical and clinical trials for both imaging and treating cancers and cancer stem cells that overexpress CD44." (PMID 34827550, 2021). "have suggested that there is a subpopulation of cells CD44+/EpCAM+ with a high correlation with ALDHhigh cell populations which were previously shown to be cancer stem cells in NSCLC patients." (PMID 33868998, 2021). "This review also illuminates the role of hyaluronic acid (HA) in cancer therapy, interaction of HA with CD44, and various approaches to target CD44-overexpressed neoplastic cells." (PMID 35431911, 2021). "Incidentally, the binding of osteopontin to CD44 stimulates CD44 overexpression, providing additional binding sites for hyaluronan and other ligands and further aiding cancer progression." (PMID 34901028, 2021). "HA has dual ability to target CD44 overexpressed in cancer cells and response to hyaluronidase overexpressed in cancer cells, which endows HA-modified materails double functions with targeted release and delivery of PS." (PMID 34796163, 2021). "CD44 is a transmembrane glycoprotein which is frequently overexpressed in cancer of various origins." (PMID 34798909, 2021). "CD44 is involved in the regulation of diverse vital signaling pathways modulating cancer proliferation, invasion, metastasis, and therapy-resistance." (PMID 34837915, 2021). "Allicin treatment at higher concentrations of 50 ng/mL and 100 ng/mL significantly reduced expression of cancer stem cell surface markers CD44 and CD133 measured as median fluorescence intensity on a flow cytometer." (PMID 34071008, 2021). "Few cancer cell lines have been actually classified as being CD44-positive and CD24-negative (CD44+/CD24−), thus questioning the significance of CD24 as a CSC surface marker." (PMID 33806857, 2021). "Even though several ligands are reported for CD44, the well-characterized ones in context to cancer are HA and OPN." (PMID 34150761, 2021). "The clinical significance and prognostic value of CD44 and the potential of CD44 as a therapeutic target in cancer are also addressed." (PMID 34944493, 2021).
cancer (continued). "Consistent with its key role in cancer progression, CD44 silencing impairs chemoresistance, clonogenicity, tumorigenicity, and/or metastasis." (PMID 33810348, 2021). "Immune cells and cancer cells both express CD44 (the cell surface marker), which is required in the growth of cancer cells and metastasis." (PMID 33917319, 2021). "Western blots with lysates from three cancer cell lines demonstrate that several CD44 isoforms are unglycosylated in the anti-CD44 target regions." (PMID 33891595, 2021). "The majority of cancer cells arise from cancer stem cells (CSCs) that express surface markers similar to that of stem cells (SCs), such as CD44, CD90 and CD133." (PMID 34122412, 2021). "WRAP5:siFluc entered the cancer cell (CD44+) in line with a decrease in the BLI signal observed in subcutaneous tumors." (PMID 34069377, 2021). "The cancer cell stemness can be assessed by mammosphere forming efficiency and the cancer stem cells surface marker CD44+CD24-/low subpopulation." (PMID 34386417, 2021). "It has been shown that HA is involved in cancer cell, lymphocyte, and neutrophil motility in a CD44-dependent manner, however, the expression of this receptor alone was insufficient for chemotaxis towards HA." (PMID 33540535, 2021). "To examine the effect of SMF on cancer stemness in mice, we used immunohistochemistry staining to detect the expressions of C-myc, Sox2, and CD44." (PMID 34917231, 2021). "Targeting and inhibiting overexpressed cancer-specific receptors on the surface of cancer cells such as CD44 and receptor for HA-mediated motility (RHAMM) is one of cancer therapy strategies." (PMID 34067587, 2021). "Alternative splicing generates various isoforms of CD44 that appear and disappear at various stages of cancer development." (PMID 34257584, 2021). "The DOX-loaded HA-SS-MP NPs showed a higher drug release at pH 5 in the presence of GSH than the physiological pH 7 and a higher uptake by cancer cells with an upregulated CD44 expression." (PMID 34361141, 2021). "In the present study, loss of PTEN in FTE led to the enrichment of cancer stem cell markers such as LGR5, WNT4, ALDH1, CD44." (PMID 33828085, 2021). "Several studies report the enrichment of cancer stem cell features such as high expression of the CD44+/CD24- immunophenotype in these cells." (PMID 34367990, 2021). "High CD44 levels have also been discovered as a marker for cancer stem cells in many other solid malignant tumors, modulating intracellular pathways via protein interactions and STAT3 signal transduction." (PMID 34067416, 2021). "CD44+ ESA+ CD24+ cancer cells demonstrate characteristics of stem cells including increased developmental signaling pathway (including SHH) leading to chemoresistance." (PMID 33836674, 2021). "GRP78 promotes self-renewal in CSCs, as well as upregulates the expression of CSC markers, including the ALDH1 and CD44, thereby contributing to cancer recurrence and resistance to chemotherapy." (PMID 34149413, 2021). "Robust evidence supports that CD44 isoforms are closely related to the clinicopathological features of numerous cancers." (PMID 34944493, 2021). "The data from the current study indicated that a higher frequency of CD44-/CD24- cancer cells, like higher frequency of CSCs, was one of the independent risk factors for delayed distant metastasis and worse DFS in this population." (PMID 34318746, 2021). "All cell lines showed distinct interaction patterns with prey receptors, and MET, CD44, and integrin5a showed the highest average shifts in cancer cell lines—13.38%, 11.10%, and 10.15%, respectively." (PMID 33603128, 2021). "Prior studies indicate that full-length CD44 can transit to the nucleus where it plays a role in cancer stem cell colony formation." (PMID 33822772, 2021). "Initial studies identified cancer stem cell markers including CD44 and ALDH in head and neck malignancies and found that these cells show aggressive features in both in vitro and in vivo studies." (PMID 35047489, 2021).
cancer (continued). "Hyaluronic acid (HA) has been widely used as an active targeting ligand due to its specific interaction with the receptor CD44 overexpressed in various malignant tumors." (PMID 33504007, 2021). "We next screened the cell lines for cancer stem cell markers by staining for CD44, CD24 and prominin-1 (CD133)." (PMID 33924486, 2021). "The surface marker proteins used extensively to identify cancer stem cells include the transmembrane glycoprotein, CD44, the cell adhesion protein, CD24, and the cytosolic enzyme, ALDH-1, which oxidizes aldehydes to carboxylic acids." (PMID 33804152, 2021). "Since CD44 appears to be a potential marker linking cancer and meDNA, we analyzed its splicing in more detail in ALL patients." (PMID 34086943, 2021). "CD44, a common marker among many cancer types, is a transmembrane hyaluronic acid receptor involved in cell adhesion, migration, metastasis, and drug resistance." (PMID 34361141, 2021). "CD44 promotes cancer cell migration and invasion by directly interacting with MMP-9, which degrades collagens." (PMID 34685653, 2021). "When cancer stem-like cells (CD44(+)) treated with genistein inhibited CD44 mRNA and Gli1 protein expressions." (PMID 34336089, 2021). "CSCs were characterized by the expression of the stem cell markers TWIST, the epithelial cell adhesion molecule (EPCAM), the transcription factors SNAI1 (SNAIL) and SNAI2 (SLUG) and cancer markers such as CD44 and prominin-1 (CD133)." (PMID 34445612, 2021). "Cancer cells overexpress CD44 and allow HA − PTX + RTV − NMF absorption, and consequently, more accumulation selectively in MCF-7 and MDA-MB-231 compared to MCF-12A." (PMID 33513992, 2021). "This has prompted other markers to be used in parallel with CD44 when examining the metastatic potency and cancer-initiation capability of cells." (PMID 34579762, 2021). "Some of the APA targets are surface receptors with well-known involvement in cancers (CD44, CD47, and CD59)." (PMID 34521731, 2021). "CD44 is a classic cancer stem cell marker and it is closed related to TGF- β-induced EMT in the A549 cell line." (PMID 34503180, 2021). "This suggests that, in addition to CD44 expression, the uptake of 1 is related to the tumorigenic status of the cancer cells." (PMID 34234213, 2021). "Cisplatin-resistant oral squamous cell carcinoma (OSCC) cells exhibit an enriched putative cancer stem–like signature with increased expression of CD44 and Oct-4 and enhanced sphere-forming ability, coupled with the acquisition of an EMT phenotype." (PMID 33718169, 2021). "It was recently found that the replication of HBV is positively correlated to the expression of cancer stemness markers (EpCAM, CD44, CD133, NANOG, OCT4, and Sox2), tumorigenesis, and self-renewal." (PMID 33669204, 2021). "GLI1 is overexpressed in BCSCs characterized by CD44+/CD24- phenotype compared to other cancer cells and is important for EMT and metastatic progression." (PMID 34889737, 2021). "For disrupting cancer stemness, apigenin (40 μM) decreases expression levels of CD44, CD105, Nanog, Oct4, VEGF and REX-1." (PMID 34769099, 2021). "Overall, the results show that HA-nCQDs can be used for imagingof CD44-specific tumors in preclinical models of human cancer andpotentially used as carriers for targeted drug delivery into CD44-richcells." (PMID 33355448, 2021). "Since CD44 is recognized as a pivotal marker for the cancer stem cells, a correlation with malignant clinicopathological characteristics and the worse prognosis seems consistent." (PMID 33009929, 2021). "HA is a biocompatible, biodegradable, and nonimmunogenic biopolymer capable of actively targeting cluster of CD44 on cell surface receptors overexpressed in many cancer cells, including TNBC." (PMID 34867360, 2021). "CSCs can be characterized from other cancer cells by expression of surface markers such as CD44, CD133, and CD24." (PMID 33925129, 2021).
cancer (continued). "CD44 is another cancer stem cell marker in CAFs, related to cancer cell survival and drug resistance." (PMID 34337083, 2021). "CD44 knockdown experiments and anti-CD44 antibodies have been shown to affect a number of cancer cell-related behaviors in vitro." (PMID 33891595, 2021). "Here, we found that GBP5 knockdown decreased several chemotherapy resistance-associated cancer stemness markers such as ALDH1A1, ALDH1A2, CD44, CD166, and ABCG2." (PMID 34439200, 2021). "It lowered the expression of CSC markers CD44, ABCG2, Sox2, and Nanog, attenuated cancer stem cell-associated spheroid formation, and inhibited the JNK signaling pathway." (PMID 34884848, 2021). "ER+ BC cells grown in coculture with DLL4+-HMVECs had higher levels of gene expression of cancer stemness-related genes (CD44, ALDH1A1, KLF4, and CD36) and PKD-1, as compared to ER+ BC cells grown in monoculture." (PMID 34168243, 2021). "The majority of prostate cells in cancer specimens had CD44-/CD24- phenotype with reduced CD44-/CD24+ cell fraction compared to BPH." (PMID 34019593, 2021). "We conclude that CD44-driving EMT processes via the Akt pathway plays a vital role in cancer metastasis in CCA by promoting cell migration." (PMID 33780455, 2021). "In a previous work of our research group, we evaluated the role of several KIF11 inhibitors on cancer stem cell (CSC) population in MDA-MB-231 cells throughout the analysis of CD44 and CD24 expression." (PMID 34548908, 2021). "Since the original description in 1996, the interaction between the cytokine osteopontin (OPN) and the homing receptor CD44 has been extensively studied in cancer, inflammation, bone remodeling, and various other conditions." (PMID 34070790, 2021). "Further, there is ample evidence that CD44 is a cancer stem cell marker and that its overexpression enhances the invasion of cancer stem cells (CSCs)." (PMID 33981532, 2021). "Real-time PCR showed that CD44, N-cadherin, and β-catenin mRNAs were highly expressed in cancer tissues, while CD24 mRNAs were low in expression compared with adjacent tissues (P < 0.05)." (PMID 34789199, 2021). "Using bioinformatics, we successfully identified CCND1/CDK4/PLK1/CD44 as oncogenic signatures, which drives cancer progression and resistance to treatment, and as potential druggable candidates for both NSC7565600 and NSC765691 small molecules." (PMID 34063946, 2021). "Intriguingly, bioinformatic analysis revealed that CCL2 and LDHA were both strongly increased in M-BCSCs population (CD44+ cancer cells) compared with the bulk cancer cells according to the GSE115302 data set." (PMID 34178639, 2021). "CRSP8 silencing significantly suppressed tumorsphere formation ability and expression levels of cancer stemness-related markers, including CD133 and CD44, while its overexpression caused the opposite effects." (PMID 33162555, 2021). "The expression of CD44 increases the invasion of cancer cells by increasing in proteases and decreasing the expression and enzymatic activity." (PMID 34804499, 2021). "The overexpression of various CD44 isoforms depends on different cell types and stages—the fate of cancer cells regulated by isoforms, CD44v, and standard CD44s." (PMID 34513617, 2021). "As a result, several RNAi-delivered nanoparticles were designed for cancer therapy through silencing CD44 individually or combined with other antitumor drugs." (PMID 34959397, 2021). "Previous studies on the colon found that CD44 pattern of staining was mainly membranous and there was a highly significant difference between carcinoma cases and normal cases (p = 0.02), which is in line with our findings with respect to CD44 expression." (PMID 34837915, 2021). "In fact, Western blot analysis confirmed that most patient-derived carcinoma specimens presented a modest level of CD44." (PMID 34073987, 2021). "Levels of the expression of CD44 and RHAMM have been associated with the progression of different types of cancer." (PMID 32610620, 2020).